CSE1L (chromosome segregation 1 like)
Diseases named in the same sentence as CSE1L in open-access papers (continued):
Sharing a sentence is not in itself a finding about the gene and the disease.
osteosarcoma (6 papers, 2017 to 2024). A usually aggressive malignant bone-forming mesenchymal neoplasm, predominantly affecting adolescents and young adults. "In osteosarcoma cells, CSE1L, a positive regulator of MSH6 protein, is associated with poor patient prognosis." (PMID 39430746, 2024). "Through clinical analysis and functional evaluation, it was found that the human CSE1L gene on chromosome 20q13 was associated with osteosarcoma tumorigenesis." (PMID 28387323, 2017). "Further validation showed that increased CSE1L expression in osteosarcoma was associated with poor prognosis and that there was a positive correlation between CSE1L and MSH6 in osteosarcoma." (PMID 28387323, 2017). "In the present study, co-immunoprecipitation was used to examine the underlying mechanism of CSE1L in osteosarcoma." (PMID 28387323, 2017). "Another study indicated that CSE1L could interact with the gene mutS homolog-6 and was also associated with a poor prognosis in osteosarcoma patients." (PMID 31371628, 2019). "To date, the role of CSE1L and the underlying mechanism in osteosarcoma are largely unclear." (PMID 28387323, 2017). "To date, little is known about the function and underlying mechanism of CSE1L in osteosarcoma." (PMID 28387323, 2017). "Therefore, CSE1L associates with MSH6 in osteosarcoma cells." (PMID 28387323, 2017). "For example, CSE1L silencing inhibited osteosarcoma cell proliferation in vitro and hampered tumor growth in osteosarcoma xenograft models." (PMID 30144787, 2018). "This present study demonstrated that knockdown of CSE1L inhibited osteosarcoma cell growth in vitro and in vivo." (PMID 28387323, 2017). "Further analysis found that CSE1L level was positively correlated with recurrence (P < 0.001), indicating that CSE1L has an important role in osteosarcoma recurrence." (PMID 28387323, 2017). "Through clinical screening and a functional evaluation, chromosome segregation 1-like (CSE1L) protein was found to be related to the growth of osteosarcoma cells." (PMID 28387323, 2017). "Taken together, these results indicate that CSE1L knockdown hinders tumorigenesis of osteosarcoma cells in vivo." (PMID 28387323, 2017). "In the present study, we show that knockdown of CSE1L inhibits osteosarcoma growth in vitro and in vivo." (PMID 28387323, 2017). "Based on these findings, CSE1L is correlated with MSH6 in tumor samples and is associated with poor prognosis in patients with osteosarcoma." (PMID 28387323, 2017). "Next, a CCK-8 assay was used to detect cell proliferation, and we found that knockdown of CSE1L significantly inhibited the growth of osteosarcoma cells." (PMID 28387323, 2017). "To further determine the clinicopathological significance of CSE1L in osteosarcoma, we performed IHC analysis of CSE1L in a tissue microarray that includes an independent set of 157 cases of osteosarcoma." (PMID 28387323, 2017). "Collectively, knockdown of CSE1L dramatically inhibits osteosarcoma cell growth in vitro and in vivo." (PMID 28387323, 2017). "Taken together, the results showed that CSE1L may have an important role in osteosarcoma tumorigenesis and thus warrants further investigation." (PMID 28387323, 2017). "Notably, CSE1L expression was correlated with MSH6 expression in tumor samples and was associated with poor prognosis in patients with osteosarcoma." (PMID 28387323, 2017). "The results showed that CSE1L was overexpressed in osteosarcoma tissues, which indicates CSE1L may have an important role in osteosarcoma tumorigenesis." (PMID 28387323, 2017). "Consequently, findings from these previous studies and the converging lines of evidence from our present study strongly indicate that CSE1L is an important regulator of osteosarcoma progression." (PMID 28387323, 2017). "More importantly, this study is the first to provide experimental evidence for the significance of the interaction between CSE1L and MSH6 in osteosarcoma cells, and reveals the molecular mechanism that may underlie CSE1L-mediated tumorigenesis." (PMID 28387323, 2017).
osteosarcoma (continued). "Our findings demonstrated that knockdown of CSE1L inhibited osteosarcoma cell proliferation." (PMID 28387323, 2017). "Analysis of clinical data revealed that CSE1L was overexpressed in osteosarcoma tissues compared to non-tumor tissues and that increased CSE1L expression in osteosarcoma was associated with a higher recurrence rate and poor survival." (PMID 28387323, 2017). "Taken together, our findings demonstrate that CSE1L is an oncogene in osteosarcoma, and thus may be a potential target for osteosarcoma treatment." (PMID 28387323, 2017). "In addition, the cell apoptosis assay showed that knockdown of CSE1L promoted the cell apoptosis in osteosarcoma cells." (PMID 28387323, 2017). "However, the role of MSH6 in osteosarcoma is unknown, and whether CSE1L functions through MSH6 is largely unknown." (PMID 28387323, 2017). "Furthermore, CSE1L expression may be a sensitive biomarker for prognosis of patients with osteosarcoma." (PMID 28387323, 2017). "Since CSE1L interacts with MSH6 and affects its protein expression and stability in osteosarcoma cells, it is plausible that CSE1L functions through MSH6 and that MSH6 has an important role in osteosarcoma cell proliferation." (PMID 28387323, 2017). "To investigate the underlying mechanism, we used co-immunoprecipitation and RNA-seq techniques and found that CSE1L interacted with and functioned through MSH6 in osteosarcoma cells." (PMID 28387323, 2017). "A rescue study showed that decreased growth of osteosarcoma cells by CSE1L knockdown was reversed by MSH6 overexpression, indicating that the activity of CSE1L was an MSH6-dependent function." (PMID 28387323, 2017). "By co-immunoprecipitation and RNA-seq analysis, CSE1L was found to interact with mutS homolog 6 (MSH6) and function as a positive regulator of MSH6 protein in osteosarcoma cells." (PMID 28387323, 2017). "We found that there was a significant correlation between expression of both CSE1L and MSH6 in osteosarcoma tissues (R = 0.697, P < 0.001)." (PMID 28387323, 2017). "In addition to presenting evidence supporting an interaction between CSE1L and MSH6, we found that CSE1L and MSH6 were co-localized in cells from two different osteosarcoma cell lines." (PMID 28387323, 2017). "This is the first study to demonstrate an interaction between CSE1L and MSH6 in osteosarcoma cells." (PMID 28387323, 2017). "The results revealed that mRNA expression of CSE1L was increased in osteosarcoma tissues than in the corresponding non-tumor tissues." (PMID 28387323, 2017). "Consequently, these results support the conclusion that CSE1L interacts with MSH6 and functions as a positive regulator of MSH6 protein in osteosarcoma cells." (PMID 28387323, 2017). "Therefore, intervention via the CSE1L/MSH6 axis may be a feasible and effective strategy in the treatment of osteosarcoma." (PMID 28387323, 2017). "In addition, a positive correlation between CSE1L and MSH6 was found in osteosarcoma." (PMID 28387323, 2017). "However, the results from migration and invasion assays showed that CSE1L knockdown did not affect migration or invasion of osteosarcoma." (PMID 28387323, 2017).
colon cancer (5 papers, 2013 to 2023). "Similarly, CSE1L overexpression in COLO 205 colon cancer cell line was associated with an increase in the invasive ability of the cells." (PMID 23369209, 2013). "Nevertheless, the data showed that enhanced CSE1L expression increased the in vivo metastasis of HT-29 colon cancer cells to the livers of the SCID mice." (PMID 23369209, 2013). "Nevertheless, our data showed that enhanced CSE1L expression increased the metastasis of HT-29 colon cancer cells to the livers of the mice, although obviously the tumor lesions were bigger in liver tumors induced by HT-29-EV cells than that induced by HT-29-CSE1L cells." (PMID 23369209, 2013). "The mRNA levels of DKC1, CSE1L and NSUN5 were higher in the colon cancer tissues than in the paired adjacent normal tissues, while the level of FLNA was lower (p < 0.05)." (PMID 36319976, 2022).
lung carcinoma (4 papers, 2021 to 2024). "In lung cancer, CSE1L interacts with p65 and regulates MAPK signaling." (PMID 39430746, 2024). "CSE1L promotes the nuclear accumulation of transcriptional coactivator TAZ and enhances invasiveness and malignancy in human lung cancer and glioblastoma cells." (PMID 34503105, 2021). "Conversely, CSE1L silencing blocked TAZ-promoted colony formation, motility, and invasiveness in human lung cancer and glioblastoma cells." (PMID 34022224, 2021).
glioblastoma (3 papers, 2010 to 2021). The most malignant astrocytic tumor (WHO grade IV). "The results of array-based comparative genomic hybridization showed that 57.1% of the glioblastoma multiforme cases had high-frequency amplification of the CSE1L gene." (PMID 20701792, 2010).
pancreatic cancer (3 papers, 2021 to 2024). "The database showed that higher CSE1L expression was associated with worse outcomes in pancreatic cancer patients (P = 0.0054).We next analyzed the correlation between CSE1L expression levels and the clinicopathological parameters of pancreatic cancer patients by the UALCAN database." (PMID 33854580, 2021). "Of note, HPSC sEVs contained dramatically more CSE1L (chromosome segregation 1–like protein), a described marker of poor prognosis in patients with pancreatic cancer." (PMID 36332889, 2022). "To investigate the function of CSE1L in pancreatic cancer, we overexpressed and suppressed its expression in pancreatic cancer cells." (PMID 33854580, 2021). "To further determine the clinicopathological significance of CSE1L in pancreatic cancer, we performed IHC analysis of CSE1L in a tissue microarray that included an independent set of 90 cases of pancreatic cancer tissues." (PMID 33854580, 2021). "Of the 90 tumor tissue samples, high CSE1L protein levels were found in 60% (54 of 90) of pancreatic cancer tissues, compared with only 35.4% (28 of 79) of normal tissues (p = 0.0013)." (PMID 33854580, 2021). "Taken together, our findings suggest that CSE1L offers significant clues for further study of the mechanism and clinical therapy of pancreatic cancer." (PMID 33854580, 2021). "The results revealed that the AKT/mTOR signaling pathway is crucial for CSE1L-mediated pancreatic cancer proliferation." (PMID 33854580, 2021). "Next, we performed loss-of-function and gain-of-function assays to explore the function of CSE1L of pancreatic cancer in vitro and in vivo." (PMID 33854580, 2021). "To investigate the functional roles of CSE1L in pancreatic cancer progression, we knocked down CSE1L via independent siRNAs significantly in PANC1, AsPC1, CFPAC1 cells." (PMID 33854580, 2021). "We also analyzed prognosis of CSE1L expression and its correlation with the clinicopathological features of pancreatic cancer." (PMID 33854580, 2021). "In the present study, we examined CSE1L expression in pancreatic cancer tissues using three online datasets and our own tissue samples." (PMID 33854580, 2021). "In the present study, we found that high CSE1L expression was related to a worse prognosis in patients with pancreatic cancer according to data from the Cancer Genome Atlas (TCGA) database." (PMID 33854580, 2021). "Taken together, these results indicated that CSE1L acted as an important tumor driver in pancreatic cancer proliferation." (PMID 33854580, 2021). "In the present study, the association between a negative prognosis and high CSE1L expression in pancreatic cancer was demonstrated." (PMID 33854580, 2021). "Moreover, the ONCOMINE database showed that CSE1L exhibited higher mRNA expression in pancreatic cancer tissues." (PMID 33854580, 2021). "Furthermore, to better understand the impact of CSE1L gene expression on the overall survival of pancreatic cancer patients, we utilized the TCGA data to assess the prognostic value of CSE1L." (PMID 33854580, 2021). "More importantly, these findings suggest that CSE1L may serve as a potential prognostic and therapeutic target for pancreatic cancer." (PMID 33854580, 2021). "Additionally, we found that CSE1L knockdown inhibited the proliferation of pancreatic cancer cells and promoted apoptosis, while CSE1L overexpression demonstrated the opposite phenomenon." (PMID 33854580, 2021). "In summary, we reveal that CSE1L plays a crucial role in tumor growth and may serve as a potential prognostic and therapeutic target for pancreatic cancer." (PMID 33854580, 2021). "We demonstrated that CSE1L promoted the proliferation of pancreatic cancer." (PMID 33854580, 2021). "In pancreatic cancer, CSE1L may regulate proliferation through the AKT signaling pathway." (PMID 39430746, 2024). "However, the role and underlying mechanism of CSE1L in pancreatic cancer is still not fully explicit." (PMID 33854580, 2021).
pancreatic cancer (continued). "In addition, CSE1L might promoted proliferation of pancreatic cancer by targeting the AKT signaling pathway." (PMID 33854580, 2021). "Therefore, CSE1L can serve as a potential prognostic indicator and treatment for pancreatic cancer." (PMID 33854580, 2021). "However, the biological function and the underlying mechanism of CSE1L in pancreatic cancer are still not fully explicit." (PMID 33854580, 2021). "Therefore, we identified CSE1L as the exportin with the greatest potential that may play vital roles in pancreatic cancer." (PMID 33854580, 2021). "CSE1L was found to be associated with a negative prognosis in pancreatic cancer patients." (PMID 33854580, 2021). "Furthermore, we discovered that CSE1L might regulate pancreatic cancer proliferation through AKT signaling pathway." (PMID 33854580, 2021). "The expression of CSE1L was much higher in pancreatic cancer cell lines than in normal human pancreatic ductal cells." (PMID 33854580, 2021).
Barrett esophagus (2 papers, 2021). Esophageal lesion lined with columnar metaplastic epithelium which is flat or villiform. "In addition, a recent study revealed that the abnormal expression of CSE1L was correlated with neoplastic progression in Barrett’s esophagus." (PMID 33842377, 2021). "The expression levels of CSE1L, RPS15A, SFPQ, and CAPZB in ESCC were significcantly higher than those in normal tissue and esophageal adenocarcinoma (EAC)." (PMID 33842377, 2021).
colon adenocarcinoma (2 papers, 2019). "In previous work PPM1H was also reported to be overexpressed in colon adenocarcinoma and co-immunoprecipitated with the CSE1L apoptosis regulator that was suggested to comprise a substrate for PPM1H." (PMID 31663853, 2019). "Moreover, protein phosphatase-1 could interact with CSE1L to control the cell cycle and the proliferation of cancer cells through CSE1L dephosphorylation in colon adenocarcinoma." (PMID 31371628, 2019).
colorectal tumor (2 papers, 2013 to 2015). "Analysis of the survival data showed that high cytoplasmic CSE1L staining in colorectal tumors was associated with a relatively poor overall patient survival rate, compared with cases displaying low staining." (PMID 23369209, 2013). "Our results showed that although high cytoplasmic CSE1L staining in colorectal tumors was associated with a lower overall survival rate compared with cases displaying low cytoplasmic CSE1L expression, the difference was not statistically significant." (PMID 23369209, 2013). "CSE1L regulates the invasiveness and metastasis of cancer cells, and immunohistochemical analysis of cytoplasmic CSE1L in colorectal tumors may provide a useful aid to prognosis." (PMID 23369209, 2013). "Analysis of the nuclear and cytoplasmic distribution of CSE1L in colorectal tumors might provide valuable clinical-pathological information to aid physicians in making decisions about treatment." (PMID 23369209, 2013). "Expression of CSE1L in non-neoplastic colorectal glands was used as an internal control and provided a scoring baseline for CSE1L staining in colorectal tumors." (PMID 23369209, 2013).
diabetes (2 papers, 2022 to 2025). "No data regarding CSE1L and diabetes are available, making its role in T2D-related OSCC questionable." (PMID 35634436, 2022).
endometrial carcinoma (2 papers, 2010 to 2019). A malignant tumor arising from the epithelium that lines the cavity of the uterine body. "Pathological studies showed that the expression of CPP32 was positively correlated with CSE1L expression in endometrial carcinoma (p = 0.008)." (PMID 20701792, 2010). "An analysis of 89 endometrial carcinomas and 56 samples of non-neoplastic adjacent endometrium showed that CSE1L was expressed in 93% of endometrial carcinomas neoplastic tissues, while lower levels of CSE1L expression were observed in the adjacent endometrium compared to the carcinomas (p = 0.003)." (PMID 20701792, 2010).
esophageal cancer (2 papers, 2021). A primary or metastatic malignant neoplasm involving the esophagus. "Lower expression of CSE1L was associated with longer overall survival in esophageal cancer patients." (PMID 33842377, 2021). "However, the role of CSE1L has not been studied in esophageal cancer." (PMID 33842377, 2021).
lymph node metastasis (2 papers, 2013 to 2021). "The Cox proportional hazards model (univariate analysis) showed that for patients with high cytoplasmic CSE1L expression, survival was significantly associated with tumor size, lymph node metastasis, and TNM stage." (PMID 23369209, 2013). "CSE1L over expression is correlated with cervical lymph node metastasis in T3–T4 glottic cancers and this may change the approach to neck treatment of larynx cancers." (PMID 31383592, 2021).
oral cancer (2 papers, 2021 to 2024). "CSE1L could also promotes the proliferative and migratory abilities in oral cancer by positively regulating MITF and activating the Akt/mTOR pathway." (PMID 39430746, 2024).